SLAMF1 (signaling lymphocytic activation molecule family member 1)
Diseases named in the same sentence as SLAMF1 in open-access papers (continued):
Sharing a sentence is not in itself a finding about the gene and the disease.
tumor (43 papers, 2013 to 2026). "Here, we generated SLAMF1-deficient EBV+ tumor cells and examined the effect of its deficiency on cell proliferation and cell survival." (PMID 32886706, 2020). "Patients with high levels of SLAMF1 expression had a better survival rate than those with low expression, suggesting SLAMF1 to be a marker for improved anti-tumor activity." (PMID 38476238, 2024). "In the human CRC TME, SLAMF1 was detected on tumor-specific innate lymphoid cells, and these cells were observed at higher levels in patient blood than in healthy controls." (PMID 38476238, 2024). "SLAMF1 is known to mediate the survival and growth of tumor cells by activating a PI3K/Akt/mTOR signaling pathway, which is involved in regulating cell metabolism, proliferation, and survival." (PMID 37251372, 2023). "While, in tumor cells, SLAMF1 has been found to be up-regulated, and it regulates cell growth and survival." (PMID 37251372, 2023). "Signaling lymphocytic activation molecule family member 1 (SLAMF1) selectively expressed on tumor-specific ILCs, and it is an anti-tumor biomarker in CRC." (PMID 37304260, 2023). "We explained that SLAMF1 and TRAF3IP3 were low-expressed in HBV-associated HCC tissues and were correlated with tumor recurrence." (PMID 36281288, 2022). "In conclusion, SLAMF1 and TRAF3IP3 were identified with higher expression in tumor tissues and associated with tumor recurrence." (PMID 36281288, 2022). "The TCGA database showed that the expression of CD2, FGL2, LAT2, and SLAMF1 in tumor tissues was significantly lower than that in cancer tissues, which was confirmed by western blotting experiments." (PMID 35602471, 2022). "SLAMF1 is commonly expressed in the immune system, and it was recently found to be expressed in tumors of the central nervous system." (PMID 33766042, 2021). "Based on TCGA and GTEx data, the mRNA expression levels of LY9 and SLAMF1 were significantly higher in tumor tissues than in normal ovarian tissues." (PMID 34461858, 2021). "In tumor cells, ligation of SLAMF1 resulted in transient phosphorylation of Akt or dephosphorylation depending on cellular context." (PMID 32886706, 2020). "The SLAMF1-dependent entry of therapeutic MV allows efficient viral spread, tumor regression, and prolonged survival." (PMID 29662641, 2018). "Elevated SLAMF1 expression may contribute to immune dysregulation and tumour immune evasion by altering the function of T cells and other immune cells." (PMID 40078069, 2025). "In addition to this normal context, single-cell transcriptomic analysis has revealed that signaling lymphocytic activation molecule family member 1 (SLAMF1) is selectively expressed on CRC tumor-specific ILCs." (PMID 35402443, 2022). "Moreover, increased cytotoxic activity against cancerous cells and IFN-secretion are the result of the up-regulation of SLAMF1 in T cells that decrease the tumor progression index in xenografted mice." (PMID 29662641, 2018). "Moreover, SLAMF1 expression in ILCs had been discovered as an anti-tumor biomarker in CRC." (PMID 36032085, 2022). "Furthermore, compared with adjacent nontumor tissues, TRAF3IP3 and SLAMF1 were highly expressed in tumor tissues and were linked to tumor recurrences." (PMID 36281288, 2022). "SLAMF1-high ILCs could serve as an anti-tumor biomarker in CRC." (PMID 35402443, 2022). "A three-gene signature (SLAMF1, CD27, SELL) model related to the tumor microenvironment was constructed to assess patient survival." (PMID 33766042, 2021). "SLAMF1 and CDC25C were also identified as anti-tumor biomarkers in CRC." (PMID 36506313, 2022). "The results showed that SLAMF1 and TRAF3IP3 were inversely associated with tumor recurrence, regardless of gender, age, tumor stage (T), lymph node stage (N), and metastasis stage (M)." (PMID 36281288, 2022). "SLAMF1 is induced in activated normal B and T lymphocytes, dendritic cells and macrophages as well as EBV-infected lymphoblastoid cell lines (LCLs) and latency type III tumor cells." (PMID 28445949, 2017).
tumor (continued). "In particular, SLAMF6 and SLAMF1 expression in TAMs was increased by LFC = 2.1 and 3.5, both p.adj < 0.0001, and CXCL13 (LFC: 6.4, p.adj < 0.0001) and CXCR5 (LFC: 1.8, p.adj = 0.001) were highly upregulated in macrophages from the tumor compared to those from a normal lung." (PMID 33918618, 2021).
cancer (12 papers, 2018 to 2024). A tumor composed of atypical neoplastic, often pleomorphic cells that invade other tissues. "For instance, the upregulation of various dendritic cell (DCs) markers, including CD80, CD274, and SLAMF1, was associated with improved overall survival (OS) in a mixed cancer analysis." (PMID 38476238, 2024). "In Epstein-Barr virus (EBV)-positive B cell lymphoma cell lines, SLAMF1 has been associated with drug resistance and promoted cancer cell survival." (PMID 37251372, 2023). "SLAMF1 has been detected in various cancer types, but its role in prognosis remains to be established." (PMID 38476238, 2024). "Other important genes in this list downregulated by TOX2-shRNA, such as ITGB7, SLAMF1, CD244, DPYSL3, KRT80 and KRT7, have been implicated in cancer progression or drug resistance." (PMID 37032358, 2023). "On the basis of GSE136247 and GSE121248, the expression of each gene in cancer tissue and normal tissue was verified, and two key genes were finally obtained, namely, SLAMF1 and TRAF3IP3." (PMID 36281288, 2022). "Similarly, using SLAMF1 expression in cancer cells, the MV oncolytic virotherapy could serve as an alternative therapy against Epstein-Barr Virus (EBV)-positive diffuse large B-cell lymphoma." (PMID 29662641, 2018).
CNS tumors (2 papers, 2015 to 2024). "Here, for the first time, we report the expression of CD150/SLAMF1 in CNS tumors." (PMID 25710480, 2015).
bacterial infection (1 paper, 2020). "It has been described that SLAMF1 positively regulates ROS production by NOX2 and phagosome maturation in response to bacterial infection." (PMID 32925918, 2020).
cardiovascular disease (1 paper, 2023). "Furthermore, many of the age-associated proteins such as CST5, CCL23, SLAMF1, MMP-1, MCP-1, and CDCP1 have been linked to chronic diseases such as cardiovascular disease and neurocognitive decline in the general population." (PMID 37672793, 2023).
SLAMF1 also shares sentences with these, for which no sentence is quoted: adenocarcinoma (4 papers); Autoimmunity (3); Crohn disease (3); melanoma (3); Sepsis (3); colorectal cancer (2); lymphopenia (2); lymphoplasmacytic lymphoma (2); malaria (2); tuberous sclerosis (2); acute lymphoblastic leukemia (1); allergic asthma (1); anaplastic astrocytoma (1); anaplastic ependymoma (1); anaplastic oligoastrocytoma (1); anaplastic oligodendroglioma (1); anemia (1); angiomyolipoma (1); asthma (1); B-cell acute lymphoblastic leukaemia (1); central neurocytoma (1); CNS primitive neuroectodermal tumour (1); diffuse astrocytoma (1); diffuse large B-cell lymphoma (1); ependymoma (1); escherichia coli infection (1); glioblastoma (1); glomerulonephritis (1); Graves disease (1); heart failure (1).
A further 35 diseases each share a sentence with SLAMF1 in 1 paper.